BRCA1 (BRCA1 DNA repair associated)
Diseases named in the same sentence as BRCA1 in open-access papers (continued):
Sharing a sentence is not in itself a finding about the gene and the disease.
prostate carcinoma (continued). "The impact of germline BRCA1 mutations is more modest as the life-time risk of prostate cancer associated with these mutations has been estimated in 13%, similar to that of the general population." (PMID 30871108, 2019). "Men on active surveillance with inherited mutations in BRCA1/2 are more likely to develop aggressive prostate cancer and need to be reclassified for tumor grading in the context of the Gleason scoring." (PMID 31366128, 2019). "Specifically, germline BRCA1/2 mutations associate with increased risk and with more aggressive prostate cancer (Gleason ≥ 8), higher risk of nodal involvement, and distant metastasis at diagnosis." (PMID 31357527, 2019). "The primary goal of this proof-of-concept study was to better understand the impact of the BRCA1/2 mutation status on the immune phenotype of prostate cancer." (PMID 31549213, 2019). "Despite having high grade histology and advanced stage at diagnosis, male BRCA1/2 mutation carriers with breast and prostate cancer demonstrated a favorable 5-year survival." (PMID 29433453, 2018). "BRCA1/2 mutation associated prostate cancers have been reported to be more aggressive and associated with a worse survival compared to BRCA wild type cancers." (PMID 29433453, 2018). "Risk factors for male breast carcinoma include BRCA1 andBRCA2 mutations, Klinefelter's syndrome, altered testosterone and estrogen balance, testicular disorders, obesity, carcinoma of prostate and its treatment." (PMID 29697934, 2018). "We also explored a patient diagnosed with prostate cancer who exhibited a BRCA1 mutation in his ctDNA." (PMID 28472989, 2017). "There was a highly significant association between the prostate cancer PRS and prostate cancer risk for male carriers of BRCA1/2 mutations (OR for prostate cancer per SD increase, 1.56; 95% CI, 1.35 to 1.81; P = 3.2 × 10−9)." (PMID 28448241, 2017). "Men with a known history of BRCA1/2 mutations should be referred to a cancer genetics professional, as they are at increased risk for prostate cancer associated with such mutations." (PMID 30310725, 2017). "Germline mutations in tumor suppressors BRCA1/2 result in an increased risk of developing breast, ovarian and others, such as pancreas, stomach and prostate cancers: the neoplastic process will rise if the wild-type gene is lost or inactivated." (PMID 28055979, 2017). "The prostate cancer PRS was associated with prostate cancer risk in male carriers of BRCA1/2 mutations, with an OR of 1.56 per SD increase in PRS." (PMID 28448241, 2017). "In particular, prostate cancer risk by age 80 years for male carriers of BRCA1 mutations ranges from 7% for those at the bottom 5% of the risk distribution to 26% for those at the top 5% of the PRS distribution." (PMID 28448241, 2017). "In a study of aggressive, treatment-naïve advanced prostate cancer assessing BRCA1/2 mutations by whole genome sequencing, a 0.6% BRCA1 and 12% BRCA2 mutation rate was observed, all with biallelic inactivation, and half of which were somatic mutations." (PMID 28525389, 2017). "Male breast cancer and prostate cancer have both been associated with germline mutations in the BRCA1/2 tumor suppressor genes." (PMID 28946846, 2017). "In men under 65 years of age, carriers of mutated BRCA1 have a 1.8 fold increased risk of prostate cancer and BRCA2 carriers an 8.6 fold increased risk." (PMID 28946846, 2017). "The increased prevalence of prostate cancer in patients with germline BRCA1 and BRCA2 mutations has prompted consideration of prostate cancer screening in such patients by the IMPACT screening study." (PMID 28487881, 2017). "We performed the first GWAS, to our knowledge, in male carriers of BRCA1/2 mutations to identify common variants that modify the risks of breast and prostate cancer in these men." (PMID 28448241, 2017).
prostate carcinoma (continued). "We investigated—for the first time to our knowledge—associations of common genetic variants with breast and prostate cancer risks for male carriers of BRCA1/2 mutations and implications for cancer risk prediction." (PMID 28448241, 2017). "Inherited genetic conditions have also been associated with prostate cancer, for an elevated risk of prostate cancer has been noted in men with Lynch syndrome and men that carry BRCA1 and BRCA2 gene mutations." (PMID 29181019, 2017). "We investigated the combined effects of established breast and prostate cancer susceptibility variants on cancer risks for male carriers of BRCA1/2 mutations by constructing weighted polygenic risk scores (PRSs) using published effect estimates as weights." (PMID 28448241, 2017). "Originally, this concept of synthetic lethality implies a treatment by PARP-inhibition alone, as it is already successfully applied to breast, ovarian and prostate cancer patients defective in HR due to mutations in BRCA1/2." (PMID 29285242, 2017). "In this study, we performed the first GWAS for breast and prostate cancers in male BRCA1/2 mutation carriers enrolled in CIMBA using the custom Illumina OncoArray." (PMID 28448241, 2017). "For prostate cancer (PrCa), rare mutations inBRCA2 and BRCA1 give rise to moderately elevated risk,whereas two of ∼100 common, low-penetrance PrCa susceptibilityvariants identified so far by genome-wide association studies implicateRAD51B and RAD23B." (PMID 26964030, 2016). "We wish to test if a cohort of men with inherited risk of mismatch repair defect through BRCA1/2 or Lynch Syndrome mutations represents a target population for prostate cancer testing." (PMID 27456091, 2016). "Overall 1 of 7 (14 %) and 1 of 20 (5 %) men with BRCA1/2 mutations were positive for a diagnosis of prostate cancer." (PMID 27456091, 2016). "This patient has a rare variant (p.P421L) of CtBP1, a coregulator of BRCA1, which has been linked to risk of prostate cancer." (PMID 26485759, 2015). "This review focuses on the association of mutations in BRCA1/2 with carcinoma of the prostate, pancreas and stomach and screening for BRCA1/2 gene mutations." (PMID 26236408, 2015). "In a study on association between prostate cancer risk and SNPs in a 200 kb area around the BRCA1 gene, the strongest link was for BRCA1 p.Q356R, with the R allele preferentially transmitted to men affected with prostate cancer before the age of 50." (PMID 26485759, 2015). "Early studies reported BRCA1 mutation carriers to have a significant increased relative risk of developing prostate cancer." (PMID 26236408, 2015). "The majority of the literature proposes an association between BRCA1/2 mutations and carcinoma of the prostate, pancreas and stomach." (PMID 26236408, 2015). "Several studies indicate that male carriers of BRCA2 are at an increased risk of developing prostate cancer while men with a BRCA1 mutation are believed to have a slightly higher risk of developing prostate cancer than those who possess no BRCA1/2 mutations." (PMID 26236408, 2015). "In some studies the risk of prostate cancer associated with BRCA1/2 mutations is reported higher in men diagnosed at an older age." (PMID 26236408, 2015). "Some studies also suggest that men with prostate cancer who harbour BRCA1/2 mutations are believed to develop the disease at an early age." (PMID 26236408, 2015). "The association of BRCA1/2 gene mutations with cancer of the prostate, pancreas and stomach has been demonstrated in a number of studies as discussed in this review." (PMID 26236408, 2015). "Familial aggregation of prostate cancer has been described and the germline mutation of BRCA1/2 genes has been implicated in some research studies." (PMID 26236408, 2015). "The first group was a prospective set of 665 male BRCA1/2 mutation carriers and controls (mean age 53 years), all healthy at time of enrolment and blood donation, 21 of whom have developed prostate cancer whilst on study." (PMID 24489760, 2014).
prostate carcinoma (continued). "Of the 240 BRCA1 mutation carriers, 5 developed prostate cancer, and of the 207 BRCA2 mutation carriers, 16 individuals were diagnosed." (PMID 24489760, 2014). "Germline BRCA2 mutation confers the highest genetic risk of prostate cancer known to date at 8.6-fold in men ≤65 years, whereas the effect of BRCA1 is more modest at 3.4-fold." (PMID 24616882, 2014). "Increased prostate cancer risk and an aggressive clinical course have been reported for BRCA1 mutation." (PMID 25426449, 2014). "BRCA1/2 mutation carriers are at increased risk of developing prostate cancer and therefore, despite the limitations of screening, an unscreened cohort would be more likely to have cases of undiagnosed cancer with potential for bias." (PMID 24489760, 2014). "PARPis have also been proven to be the first treatment for BRCA1/2 mutation carrier in prostate cancer patients and have promising anti-tumor activity." (PMID 24289880, 2013). "In this study, our overall response rate was high (77%) indicating a strong interest in prostate cancer screening among Polish men with a BRCA1 mutation." (PMID 24325841, 2013). "Men determined to be BRCA1/2 mutation carriers have elevated risks for breast and prostate cancer, as well as other forms of the disease." (PMID 22257650, 2012). "Specifically, the increased risk of prostate cancer is associated with the BRCA1 4153delA and the C61G mutations." (PMID 22312502, 2011). "Other cancers that have been shown to be associated with BRCA1/2 mutations include male breast cancer, prostate cancer, pancreatic cancer, and melanoma." (PMID 19277124, 2009). "Although the increase in risk of developing breast, ovarian, and prostate cancer in BRCA1 and BRCA2 mutation carriers has been studied extensively, its impact on mortality is not well quantified." (PMID 19277124, 2009). "There were 183 men with prostate cancer who were known or probable carriers of a BRCA2 mutation and 119 men with prostate cancer who were known or probable carriers of a BRCA1 mutation." (PMID 18577985, 2008). "In this study, we compared survival of men with a BRCA2 mutation and prostate cancer with that of men with a BRCA1 mutation and prostate cancer." (PMID 18577985, 2008). "Prostate cancer incidence has been shown to be higher in BRCA1 and BRCA2 mutation carriers under the age of 65 years." (PMID 18182994, 2008). "We obtained the age at diagnosis, age at death or current age from 182 men with prostate cancer from families with a BRCA2 mutation and from 119 men with prostate cancer from families with a BRCA1 mutation." (PMID 18577985, 2008). "For example, there is a new study, IMPACT (The Identification of Men with genetic predisposition to ProstAte Cancer: Targeted screening in BRCA1/2 mutation carriers), and our study has informed the way that these men are invited into the study." (PMID 16434997, 2006). "Such mutations would account for a small proportion of cases only but the increased risk of prostate cancer in male BRCA1 and BRCA2 mutation carriers indicates some commonality in histogenetic pathways in breast and prostate carcinomas." (PMID 11875732, 2002). "Although this is a case report, early detection and treatment intervention may have the potential to lead to favorable clinical outcomes for aggressive prostate cancer patients with a BRCA1 pathogenic variant." (PMID 41423785, 2026). "On the other hand, BRCA1 pathogenic variants increase the risk of prostate cancer by 1- to 3-fold." (PMID 41423785, 2026). "However, a case report of prostate cancer with BRCA1 pathogenic variants shows a drastic clinical course and difficulty in treatment." (PMID 41423785, 2026). "In addition, we reported a case of aggressive prostate cancer with a BRCA1 germline pathogenic variant at Keio University Hospital." (PMID 41423785, 2026). "Although BRCA1 pathogenic variants might have a limited contribution to prostate cancer development, they could influence its aggressiveness." (PMID 41423785, 2026).
prostate carcinoma (continued). "BRCA1 pathogenic variants are associated with a lower risk of developing prostate cancer than BRCA2, but aggressiveness remains unclear." (PMID 41423785, 2026). "This is evident by the clinical success of poly(adenosine 5′-diphosphate–ribose) polymerase inhibition in breast cancer type 1/2 susceptibility (BRCA1/2)-altered prostate cancers and the exceptional response to checkpoint inhibitors in MSH (MutS Homolog)–altered prostate cancers." (PMID 39919177, 2025). "For instance, prostate cancer with mutations in homologous recombination repair genes such as BRCA1 and BRCA2 shows increased sensitivity to poly (ADP-ribose) polymerase (PARP) inhibitors and may benefit from platinum chemotherapy." (PMID 40027043, 2025). "Furthermore, compared to the age-matched Danish population, prostate cancer was diagnosed eight times more often than expected in men with LP/P BRCA1/2 variants, similar to the SIR of five observed in men with initial non-malignant biopsies." (PMID 39838196, 2025). "The remaining question is whether men with LP/P BRCA1/2 variants harbor a biologically aggressive form of prostate cancer that requires earlier detection and treatment than the general population." (PMID 39838196, 2025). "In prostate cancer, it was shown that AR can promote DNA repair through homologous recombination as its inhibition can mimic the loss-of-function of the breast cancer type 1 susceptibility protein (BRCA1) and confer cancer sensitivity to poly(ADP-ribose) polymerase 1 (PARP1) inhibitors." (PMID 40150035, 2025). "BRCA2 and BRCA1 variants are associated with hereditary predisposition to prostate cancer." (PMID 38996041, 2025). "The objective of this study was to investigate whether age-specific low PSA thresholds for the detection of prostate cancer should be used in men with pathogenic BRCA1/2 variants." (PMID 39838196, 2025). "However, besides ovarian, breast, and prostate cancers, BRCA1/2 mutations are rare in other tumor types." (PMID 40421223, 2025). "Timely detection of BRCA1/2 mutations is essential for identifying metastatic prostate cancer patients who may benefit from PARP inhibitor therapy." (PMID 40427202, 2025). "In breast, ovarian, pancreatic, and prostate cancers, homologous recombination (HR)–deficiency signatures were more common in tumors with new pathogenic missense mutations in BRCA1/2, PALB2, and RAD51C than in benign missense mutations (66.7% v 35.2%, P = .021)." (PMID 40570257, 2025). "We found a high incidence of prostate cancer in men with LP/P BRCA1/2 variants, but this may be explained by the low PSA threshold for scheduling biopsies." (PMID 39838196, 2025). "Germline BRCA1/2 mutations are present in approximately 6% of patients with prostate cancer." (PMID 40572035, 2025). "As the clinical course of prostate cancer in men with LP/P BRCA1/2 variants may be worse, the detection of low-grade cancer in men with LP/P BRCA1/2 variants needs to be weighed against the treatment outcomes." (PMID 39838196, 2025). "As a result, next-generation sequencing (NGS) is a key tool for detecting somatic mutations in BRCA1/2 to identify metastatic prostate cancer patients who could benefit from PARP inhibitor therapies." (PMID 40427202, 2025). "As a result of the discovery that mutations in BRCA1 and BRCA2 predispose to development and aggressiveness of prostate cancer, germline testing for BRCA1, BRCA2, and other cancer predisposition syndromes such as Lynch Syndrome is likely to gain more prominence." (PMID 38583453, 2024).
prostate carcinoma (continued). "Moreover, studies in ovarian and prostate cancer have revealed multiple-gene (e.g., BRCA1 and BRCA2) reversion mutations merely identified in progressive tumor tissues, which lead to the restoration of DNA repair function and acquired drug resistance." (PMID 39104720, 2024). "Subsequently, other PARP inhibitors combination Talazoparib + Enzalutamide, Niraparib + Abiraterone Acetate + Prednisone, were approved in 2023 for treating patients with metastatic castration-resistant prostate cancer with alterations in BRCA1, BRCA2, and HRR deficiency gene mutation." (PMID 39175508, 2024). "Interestingly, results from the TRITON2 study (NCT02952534) showed clinical activity of rucaparib was greater in castrate-resistant prostate cancer patients with BRCA2 mutations compared to BRCA1 mutations." (PMID 38965423, 2024). "Similarly, for PARP inhibitors, much of the focus in prostate cancer has been on the “synthetic lethality” mechanism, which has resulted in these agents becoming available for the treatment of patients with BRCA1/2 or ATM-loss prostate cancer." (PMID 38672592, 2024). "BRCA2 is estimated to be present in about 1-2% of sporadic prostate cancer cases, leading to an 8.6-fold increase in the risk of prostate cancer, while BRCA1 increases the risk of sporadic prostate cancer by 3.5-fold, but it is present in only 0.44% of prostate cancer cases." (PMID 39364320, 2024). "BRCA1 mutations also increase the risk of prostate cancer, although to a lesser extent." (PMID 39132508, 2024). "Prostate cancer susceptibility is influenced by the BRCA1 and BRCA2 genes." (PMID 39132508, 2024). "Here, we perform genome-wide CRISPR-Cas9 knockout screens in BRCA1/2-proficient prostate cancer cells and identify previously unknown genes whose loss has a profound impact on PARP inhibitor response." (PMID 36650183, 2023). "A prospective observational research report on the incidence of prostate cancer in western populations focused on a group of BRCA1/BRCA2 pathogenic variant carriers and a control group that underwent predictive testing and finally tested negative for a pathogenic germline BRCA1/BRCA2 variant." (PMID 37174127, 2023). "Furthermore, mutations in BRCA2 are more often associated with other types of epithelial cancer, including male BC, pancreatic cancer, and prostate cancer, than BRCA1 mutations." (PMID 36902416, 2023). "Prostate cancer harboring BRCA1/2 mutations are often exceptionally sensitive to PARP inhibitors." (PMID 36650183, 2023). "Considering the syndromes predisposing to prostate cancer, several overlaps with breast or ovarian cancer syndromes emerge: BRCA1- and BRCA2-associated hereditary cancer syndrome (gene: BRCA1/2), ATM or AT or Louis-Bar syndrome (gene: ATM), and Lynch syndrome (LS) (lft 5–16%)." (PMID 37239385, 2023). "In addition, prostate cancer had a high rate of therapeutic target mutations, including BRCA1/2, CDK12 mutations, and ERBB2 amplification." (PMID 36251535, 2023). "Moreover, the results of this meta-analysis discard the involvement of BRCA1 mutations in the development of prostate cancer." (PMID 37444562, 2023). "Likewise, the males carrying the BRCA1/2 pathogenic variant are at high risk of developing prostate cancer." (PMID 37951914, 2023). "These positive preliminary findings led to the FDA approval of rucaparib in May 2020 for BRCA1/2 mutated metastatic castration-resistant prostate cancer patients who progressed after one to two lines of AR-directed therapy and one taxane-based chemotherapy." (PMID 36010882, 2022). "Thus, our exome analysis provides evidence of distinctive germline BRCA1 mutations in prostate cancer of patients with African Ancestry." (PMID 36922933, 2022).